IL6 (interleukin 6)
Diseases named in the same sentence as IL6 in open-access papers (continued):
Sharing a sentence is not in itself a finding about the gene and the disease.
cancer (continued). "In cancer many cytokines, more notably, IL-6 was found to be elevated along with ACE2, demonstrating a possible insight of cancer-like surge of cytokines." (PMID 33981235, 2021). "Our data are in agreement with previous reports showing that p-STAT3-high cell lines from various cancer models secrete higher levels of IL-6 while p-STAT3-low cancer cell lines demonstrate low levels of IL-6 production." (PMID 34956861, 2021). "Regulation of IL-6 by activation of PI3K/NFκB has been reported in cancer cells, as well as astrocytes." (PMID 34568098, 2021). "The importance of IL-1 and IL-6 in the progression of cancer is highlighted in clinical trials of IL-1 and IL-6 antagonists on cancer survival." (PMID 34988471, 2021). "The pro-inflammatory cytokines IL-6 and IL-8 participate in various biological processes, such as alterations of the immune system and various types of cancer." (PMID 33573284, 2021). "IL-6, for example, is a biomarker indicative of prognosis for relapse-free survival and cancer recurrence." (PMID 33815828, 2021). "Recently, it was reported that IL-6, which is produced by a variety of cells, including macrophages, has an important role in cancer initiation and progression." (PMID 34885137, 2021). "For example, in the C-T network, ICT, kaempferol and sitosterol target proteins associated with inflammation, cancer cell apoptosis and migration in the TME, such as COX2, IL-6, GSK3β, CDK2 and NOS3." (PMID 33460401, 2021). "To examine the phenotypic conversion of fibroblasts in response to secretions from PGCCs or IL-6 alone, we performed immunofluorescence staining for α-SMA, a commonly used marker for cancer-associated fibroblasts (CAFs)." (PMID 34588424, 2021). "M1 macrophages kill invading pathogens and cancer cells by producing pro-inflammatory cytokines, such as IL-1β, IL-6, and TNFα." (PMID 33406733, 2021). "While IL-17A acts as a potent inducer of T-cell-mediated antitumor immune responses, this cytokine was described as an essential activator of angiogenic factors, as well as an inducer of the proinflammatory factors IL-6 and IL-8 in cancer." (PMID 34830027, 2021). "IL-6 is a multi-functional signaling protein that facilitates the inflammation cascade, as well as key pathways and processes in the cancer microenvironment and regulates many hallmarks of cancer." (PMID 35008324, 2021). "One of the most extensively studied and described pro-tumorigenic axes involved in the communication between cancer cells and their microenvironment is the IL-6/IL-6R/JAK-STAT3 pathway." (PMID 34298736, 2021). "Here the authors unravel a mechanism by which CAFs activate BRD4 and induce resistance to BET inhibitors in cancer cells through IL6/IL8 signaling." (PMID 34290255, 2021). "Recently, selective inhibitors of IL-1β, IL-6 and IL-8 are proposed in cancer patients aimed to improve anticancer effects of selective inhibitors of kinases and immune check-point inhibitors, reducing their toxicity." (PMID 34178667, 2021). "CD10+GRP77+ CAFs promote sphere formation, the proportion of ALDH+ and CD44+CD24– breast CSCs, and chemoresistance properties of cancer cells by secreting IL6 and IL8." (PMID 34760886, 2021). "Specifically, the IL-6 cytokine is an essential player in the progression of cachexia in cancer as its levels correlate with the survival of advanced cancer patients, and it is a sensitive indicator of muscle mass loss in patients with colon and lung cancer." (PMID 34944037, 2021). "We investigated the sensitivity of densities of cancer cells (C), IL-6 (L), NF-κB (F), Bcl-2 (B) and BAX (X) to these parameters at several time points." (PMID 34669701, 2021). "In a review paper, the IL-6 serum level at diagnosis was significantly correlated to survival in 82/101 series, comprising 9917 out of 11,583 patients with 23 different cancer types." (PMID 32621022, 2021).
cancer (continued). "We show that SSTP1, a novel HDP identified by shotgun cloning, binds to the active IL6/IL6Rα/gp130 complex on cancer cells, rearranging the active site residues." (PMID 34867962, 2021). "Inflammatory conditions can lead to increased expression of inflammatory cytokines, including interleukin-6, TNF, and IL-1β, which increase the risk of cancer." (PMID 34239566, 2021). "Based on the important role of TAMs-derived IL-6 in cancer, therapeutic strategies targeting the IL-6 pathway are in active development." (PMID 34717710, 2021). "This work aims to summarize the role of the IL-6 cytokine family on epithelial–mesenchymal plasticity during cancer." (PMID 34361105, 2021). "Our results further our previous observations that IL-6 augments Cisplatin-induced cancer cell stemness, implicating Cisplatin and IL-6R signaling as mediators of phenotypic changes in HNSCC tumors that result in enhanced stemness." (PMID 34689150, 2021). "They revealed that the stress-response cancer cells were colocalized with IL-6 releasing inflammatory fibroblasts, supporting the IL-6 induced stress-response mechanism in cancers." (PMID 34177965, 2021). "The cancer-associated fibroblasts further enhance expression of pro-inflammatory cytokines such as interleukin-6 and interleukin-8 in cancer cells that led to their resistance in sorafenib treatment." (PMID 33842540, 2021). "Among these signaling pathways, p38MAPK and IL-6 signaling, widely involved in various functions of cancer cells, was selected further." (PMID 34696771, 2021). "Lastly, studies in mouse HCC models have demonstrated that isolated HCC progenitor cells can give rise to cancer when there is ongoing liver damage, and that these cells promote their own growth and progress towards malignancy via autocrine IL-6 signaling." (PMID 34638361, 2021). "IL-6 secreted from cancer cells also acts in a paracrine manner to induce the differentiation of fibroblasts into CAFs." (PMID 34360868, 2021). "Interleukin 6 (IL-6), a multifunctional cytokine, not only mediate immune and inflammatory response but also participate in various hallmarks of cancer, including drug resistance." (PMID 33816512, 2021). "The IL-6 and NLR, immunologically based index, were associated with immune evasion and nutrition metabolism in cancer." (PMID 34578883, 2021). "IL-6 is frequently overproduced by CAFs in different types of cancer stimulating cancer cell proliferation, survival, invasiveness, and drug resistance." (PMID 34638245, 2021). "For example, metabolic reprogramming was found to directly affect macrophages’ polarization to the M2 phenotype, and glycolysis facilitates the secretion of IL-6 in M2 macrophages, IL-6 then enriches cancer cells with the CSC phenotype." (PMID 34638609, 2021). "In other study, DHTS has been shown to inhibit cancer stem cells (CSCs) in TNBC cell line i.e. MDA-MB-231 by activation of NOX5 mediated ROS/Stat3/IL-6 pathway." (PMID 34319041, 2021). "In cancer patients, infusions of recombinant human IL-6 significantly increased activation markers of coagulation such as thrombin-antithrombin III complexes and prothrombin fragment F1 + 2, without substantially impacting fibrinolysis." (PMID 34073768, 2021). "There is evidence that high circulating levels of IL-6 and IL-8 are markers of a poor prognosis in various types of cancer, including NB." (PMID 33573284, 2021). "Consistent with their role in cancer progression, immunomodulatory pathways, like IL6 pathway, are identified as therapeutic targets in different cancers." (PMID 34867962, 2021). "The study reported here supports a role for elevated S100B levels in suppressing IL6/STAT3 signaling providing additional evidence of S100B in supporting cancer." (PMID 34411141, 2021). "The loss of PTEN leads to aggressive expression of IL-6, IL-10 and VEGF, thereby facilitating the immune response against cancer cells." (PMID 34381028, 2021).
cancer (continued). "IL-6 released from malignant cells increases cancer cell growth in an autocrine and paracrine manner, which is important for survival and progression of cancer." (PMID 34680349, 2021). "In concordance with our results, high UCP1 production triggered by IL6 was proposed to be the leading mechanism for lipolysis and cachexia in cancer patients." (PMID 34067093, 2021). "Previous studies have indicated that IL-6 drives many of the expression of cancer ‘hallmarks’ through the downstream activation of the JAK/STAT3 signaling pathway." (PMID 33919077, 2021). "IL-6 is an important factor that regulates oncogenic signaling and is correlated with resistance to cancer treatment." (PMID 34109109, 2021). "Second, cancer cells can synthesize inflammatory cytokines, such as IL-1, IL-6, IL-8, tumor necrosis factor-α, and vascular endothelial growth factor, independently." (PMID 34232194, 2021). "IL-6 has been shown to be a survival and/or proliferation factor in certain cancers, such as kidney, ovarian, prostate, and certain types of B-cell lymphopathies, and can therefore be considered a therapeutic target." (PMID 33708198, 2021). "Moreover, IL-6 induced by MALAT1 could activate normal to cancer-associated fibroblast conversion." (PMID 33824303, 2021). "Several cellular pathways have been proven to take part in cancer-related inflammation, among which the most prominent is the NF-κB pathway and interleukin 6 (IL-6)/STAT3 signaling." (PMID 33990540, 2021). "On the other hand, the link between STAT3 and IL6 has been reported in inflammation and cancer studies." (PMID 33672392, 2021). "Functional studies using P2X7R agonists and inhibitors show that the receptor is involved in PSC proliferation, collagen secretion and IL-6 secretion and it promotes cancer cell migration in a human PSC-cancer cell co-culture." (PMID 34440697, 2021). "Accordingly, cervical cancer cells regulate DC production of IL-23 and IL-12 in DC/fibroblast cocultures through IL6/C/EBPβ/IL1β promoting Th17 cell expansion, although reducing antitumor Th1 differentiation during cancer progression." (PMID 34337083, 2021). "Inflammatory pathways are linked to carcinogenesis and progression, and cancer patients often have elevated levels of pro-inflammatory cytokines (TNF-α, IL-6, and IL-1β) and expansion of regulatory cells (myeloid-derived suppressor cells and Tregs)." (PMID 34239993, 2021). "Its functions included inhibition of IL-6R/STAT3 signaling by binding to IL-6R mRNA in cancer cells as well as inhibition of the IL-6 molecule in TAMs by CPEB3." (PMID 34944712, 2021). "These cancer subsets show immune cell infiltration and inflammation and involve pathways linked to the SARS-CoV-2 response, such as immune checkpoint, IL-6, type II interferon signaling, and NF-κB." (PMID 33510359, 2021). "Recently, a study demonstrated that a synergistic IL-6 and IL-8 signaling pathway is required to influence cancer cell motility and metastases." (PMID 34445170, 2021). "Pertaining to cancer hallmark, IL6-JAK-STAT3 signaling pathway and inflammatory response were the most relevant cancer hallmark." (PMID 35360412, 2021). "The inflamed adipocytes secrete various adipocytokines notably IL-6 and leptin that enhance carcinoma growth." (PMID 34561446, 2021). "Increased expression of IL-6 and STAT3 was demonstrated in biopsies from UC patients with active disease and in IBD-associated carcinomas, as compared to patients with inactive disease or controls." (PMID 34884543, 2021). "Strikingly, IL-6 and IL-8 expression in acid-conditioned OB was higher than those of carcinoma cells." (PMID 34124067, 2021). "Among them, anti-IL-6 monoclonal antibody (Siltuximab) has been used in clinical trials to treat cancers." (PMID 32549792, 2020). "IL-6 is a proinflammatory cytokine that is actively involved in the growth of various types of cancer, influencing and increasing the rate of metastasis." (PMID 32899735, 2020).
cancer (continued). "Interleukin-6 is a very important cancer cytokine and it is known to be capable of activating the STAT pathway." (PMID 32633727, 2020). "The IL-6-treated cancer cells (considered as CTC), colonization, and invasion were monitored using three parallel channels, lymphatic vessel channel, blood vessel channel, and the extracellular matrix between the channels." (PMID 33659239, 2020). "For instance, Nab-paclitaxel treatment increases CXCL-10 expression in pancreatic cancer cells, leading to lower IL-6 secretion by CAFs subsequently impairing migration and invasive capabilities of cancer cells." (PMID 33553157, 2020). "Some of the druggable genes were expected to correlate with non-cancer cells, including the cytokines IL6 and TGFB2, which correlated with epithelial cells and fibroblasts, respectively." (PMID 32275708, 2020). "Fibroblasts activated by exosomal lnc-POU3F3, in turn, promote the proliferation and cisplatin resistance of cancer cells through the paracrine secretion of an inflammatory cytokine, IL-6." (PMID 33050576, 2020). "Despite the similar sequence homology, structure, and intron-exon and promoter elements between OSM and LIF, the individual IL-6 cytokines have differing roles in cancer and bone biology." (PMID 32023849, 2020). "NF-κB has been shown to regulate the expression of several cytokines, in particular IL-6, in normal tissues and cancer cells." (PMID 35582225, 2020). "Among them, IL6 is a well-characterized cytokine that has been reported to be involved in various cancers progression by stimulating JAK2/STAT3 pathway." (PMID 32963220, 2020). "In cancer cells, aberrant IL-6 signaling and constitutive activation of Stat3 are closely related to cell proliferation and drug resistance." (PMID 32211606, 2020). "EVs containing TGF-β are able to induce the IL-6-signaling pathway in MSCs, favoring the differentiation into the cancer phenotype." (PMID 32717819, 2020). "The activated fibroblasts induce the pre-metastatic niche formation and promote metastatic cancer growth by secreting pro-inflammatory cytokine, such as IL-6 and IL-8." (PMID 32139701, 2020). "Plasma levels of IL-6 are generally close to the detection limit (1 pg/mL) in healthy individuals but significantly increase during the inflammatory process and cancers." (PMID 32150944, 2020). "In contrast, the CV extract-stimulated MCF-7 cancer cells only released higher levels of IL-6 compared to untreated cells, while the concentrations of IL-8 and MMP-9 were comparable with the control cells (respectively)." (PMID 33260615, 2020). "Crosstalk between astrocytes and cancer cells involves IL-6 and IL-8, which cancer cells secrete to up-regulate endothelin expression, promoting cancer progression." (PMID 32742634, 2020). "The IL-6 and prostaglandin E2 realized by platinium-treated cancer cells were responsible for polarization of macrophages." (PMID 32456078, 2020). "Stromal fibroblasts so called CAFs suppress CD8+ cells function via PDL2 and FAS-ligand, and enhance secretion of interleukin (IL)-6 via crosstalk with cancer cells resulting decreasing accumulation of CD8+ cells." (PMID 33081727, 2020). "Cav‐1 was identified to modulate the secretion of interleukin‐6 (IL‐6), which is an important factor in the microenvironment of tumor and the growth of cancer cells." (PMID 32508059, 2020). "Adipocyte-derived factors induce IL-6 production by cancer cells protecting cancer cells from radiation therapy." (PMID 32731620, 2020). "The broad acting inflammatory cytokine IL-6 has been demonstrated to play a key role in numerous cancers." (PMID 32326381, 2020). "Flavonoids have been reported to induce apoptosis of human cancer cells, inhibit NF-κB and the IL-6/STAT3-mediated inflammatory signalling pathway, and also regulate levels of inflammatory cytokines such as IL-6, IL-1β, and TNF-α." (PMID 33082817, 2020).
cancer (continued). "Studies have shown the detrimental role of inflammatory cytokines, TNF-α and IL-6, in the promotion of cancer progression." (PMID 32796516, 2020). "IL-6, a well-known inflammatory cytokine in several inflammatory forms of cancer, was elevated with little difference between the AOM/DSS and DSS only groups." (PMID 32075312, 2020). "In conclusion, our data support the contention that Nrf2 activation is an important molecular mechanism in cancer coupled with the functional involvement of IL-6/p62 in EpCAMhigh HNSCC." (PMID 32814771, 2020). "Meanwhile, all of these effects were abrogated either by adding IL6 neutralizing antibodies to the co‐cultured CM or by downregulating STAT3 or gp130 expression in cancer cells." (PMID 32308766, 2020). "TAMs produce multiple growth factors and inflammatory cytokines (IL–1β, IL–6 and TNF–α), each associated with EMT in cancer cells." (PMID 32443890, 2020). "Nevertheless, IL-6 was detected in all conditions that include cancer cells, suggesting that IL-6 is intrinsically secreted by the STn-expressing cancer cell lines used." (PMID 32370811, 2020). "Under pathological conditions like obesity and cancer, the level of IL-6 secreted by adipocytes is significantly increased." (PMID 32787888, 2020). "Similar results were observed in the liver of the C26 mice, suggesting that the regulation of these APR by IL-6 during cancer cachexia is comparable in these two organs." (PMID 33142864, 2020). "One of the multifunctional, protumoral factors of interest secreted from myofibroblasts and cancer-associated-fibroblasts (CAF), respectively, is IL-6 (e.g. 70,71), which indeed slightly enhanced the CD44 surface signal in LS1034 cell cultures." (PMID 32685007, 2020). "Several studies have highlighted the pro-cancerogenic role of tumor-infiltrated leukocytes through release of some cytokines, such as IL-6 and IL-1β, found to be increased in different cancer models." (PMID 32183434, 2020). "Some studies have highlighted the effect of the IL-6/JAK/STAT signaling pathway on cancer initiation and progression." (PMID 32283655, 2020). "There are many therapeutic approaches that recommend phytoestrogens and soy isoflavones (such as genistein, daidzein, biochanin) that aim to modulate the expression of IL-6 gene to prevent cancer progression." (PMID 32178382, 2020). "Previous studies have shown that IL-6 enhances resistance of a variety of cancers to cisplatin (DDP) treatment via activating STAT3 pathway 29-35." (PMID 32127934, 2020). "We studied the role played by these ligands, while other authors have mainly focused their attentions on IL-6 and its role in cancer cell proliferation." (PMID 31504643, 2020). "By inhibiting activin A signalling, the production of IL‐6 from the cancer cells is reduced by 40–50% (up to 42% reduction on protein level, P = 0.0048, and 48% reduction on mRNA level, P = 0.0308)." (PMID 31436048, 2020). "In fact, IL-6 receptors are upregulated in PCa cells and IL-6 plays a trophic role in cancer growth." (PMID 33312730, 2020). "In murine cancer models, HMGB1 and S100B induce muscle wasting and this is associated with elaboration of IL-1β and IL-6." (PMID 33291708, 2020). "Constitutive activation of STAT3 or NF-κB up-regulates major pro-inflammatory cytokines, such as TNFα, IL-1, and IL-6, which can promote cancer cell proliferation, angiogenesis, and metastasis." (PMID 33396715, 2020). "In particular, IL‐6 is well known as a critical regulator of STAT3 activation in most kinds of cancers." (PMID 32491253, 2020). "We show that activin A acts in an autocrine manner to promote the synthesis and secretion of IL‐6 from cancer cells." (PMID 31436048, 2020). "Peng and colleagues showed that MDSCs directly promoted and maintained cancer stemness through the interaction between IL6/STAT3 and the NO/NOTCH signaling pathway." (PMID 33091036, 2020).